MIR103B1 (microRNA 103b-1)
Synonyms: hsa-mir-103-1-as; hsa-mir-103b-1; MIR103-1AS; MIRN103-1AS
Gene: MicroRNA gene on chromosome 5 (168,560,904 to 168,560,965, forward strand). Ensembl gene ENSG00000283612.
Gene Ontology:
Biological process: miRNA-mediated post-transcriptional gene silencing
Cellular component: RISC complex